APOA1 (apolipoprotein A1)
Diseases named in the same sentence as APOA1 in open-access papers (continued):
Sharing a sentence is not in itself a finding about the gene and the disease.
tumor (continued). "Therefore, we conservatively concluded that APOA1 might act as a potential tumor suppressor gene in KIRC." (PMID 35858961, 2022). "Different from ApoA1 and ApoM, a high ApoB level may be a risk factor for HCC as it is correlated with poorer post-surgery survival in HCC patients, and individuals with higher ApoB level tend to have a larger tumor size." (PMID 36506554, 2022). "However, there are few studies on the correlation between APOA1 and tumor chemotherapy." (PMID 35421932, 2022). "Apolipoprotein A1 (APOA-1) is the main protein component of high-density lipoproteins; it has been reported to be involved in numerous biological processes, inhibiting the formation of tumor blood vessels and inducing tumor immune microenvironment to prevent malignant tumor development." (PMID 34790226, 2021). "Finally, pre-clinical studies have shown that delivery of supra-physiological amounts of HDL's major apolipoprotein, ApoA1, may itself attenuate tumor growth." (PMID 32411725, 2020). "In addition, there is an interaction between ApoA-1 and the body's inflammatory response, which reduces the rate of liver synthesis and secretion of ApoA-1, and serum low ApoA-1 concentration can indirectly lead to increased cytokine release and strong inflammatory response against tumor cells." (PMID 32391278, 2020). "Importantly, the CEA level, number of monocytes, LMR, and ApoA1 could be easily calculated in the blood, eliminating the need for invasive procedures and complex processes to evaluate the tumor immuno-microenvironment." (PMID 31300050, 2019). "Second, when injected or administered orally, ApoA-1 mimetic peptides could inhibit tumour growth and reduce the plasma levels of tumour-promoting lysophosphatidic acid (LPA) and oxidized lipids (which serve as potent tumour growth and angiogenic factors) in tumour-bearing mice." (PMID 30486825, 2018). "In the present explorative, and hypothesis generating study, we observed strong positive associations of metabolomic lipoprotein subfractions Apo-A1, HDL, and larger HDL subfractions’ contents of cholesterol, free cholesterol, phospholipids, and apolipoprotein-A1 with tumor PgR expression." (PMID 26970778, 2016). "Therefore, improving the serum ApoA-1 level in HCC patients might be a promising therapeutic strategy to limit tumor recurrence and metastasis in HCC patients post-surgery." (PMID 27683106, 2016). "Moreover, our vitro experiments implied that ApoA-1 could inhibit tumor cell proliferation and induce apoptosis." (PMID 27683106, 2016). "GO analysis showed that in the biological processes (BP) category, genes such as APOA1 and ENTPD8 were upregulated in MACCS1, suggesting a role for metabolic reprogramming in fueling tumor invasion and metastasis." (PMID 41037214, 2025). "The RT-qPCR analysis revealed significantly decreased expression of ESR1, APOA1, IGF1, PPARGC1A, SERPINE1 and PON1 in tumor tissues compared with adjacent normal tissues (P < 0.05)." (PMID 40317014, 2025). "Bioinformatics analysis revealed that APOA1, BCHE, and STARD5 were significantly expressed in normal samples, while CYP19A1 and PLA1A were considerably expressed in tumor samples in the TCGA-STAD cohort." (PMID 38357546, 2024). "Apolipoprotein A1 (Apo-A1), a predominantly expressed protein within UTUC tumor tissue, was correlated with the NLR value in the blood." (PMID 38534755, 2024). "Consequently, APOA1 may have significant potential as an anti-tumor drug." (PMID 38357546, 2024). "To further investigate cholesterol metabolism in GBMs, we examined the expression patterns of APOA1 and ABCA1/G1 on GBM cells and tumor-infiltrating immune cells." (PMID 37474548, 2023). "Meanwhile, mimetic peptides of APOA1 are known to remodel HDL, encourage the efflux of cholesterol from cells, and stimulate anti-inflammatory pathways, thus restricting tumor progression and improving survival, both in vitro and in vivo." (PMID 38067270, 2023).
tumor (continued). "We therefore exploit ectopic expression of the ABCA1/G1 ligand ApoA1 to enhance cholesterol efflux from TAMs in the GBM microenvironment, which leads to a TAM-T-cell-mediated tumor clearance." (PMID 37474548, 2023). "APOA1 has been reported to capture circulating tumor cells and promote tumor cell apoptosis by downregulating that MAPK pathway, thereby inhibiting tumor cell proliferation." (PMID 35421932, 2022). "ApoA1, a major protein component of HDL-C and a key medium for cholesterol homeostasis, plays an anti-tumor role via affecting the immune system and inhibiting new angiogenesis." (PMID 35086516, 2022). "It has also been reported that a short peptide on APOA1 regulates the phosphorylation of c-Src through the c-Src/ERK signaling pathway, thereby inhibiting tumor growth and angiogenesis." (PMID 35421932, 2022). "A total of six upregulated genes (FN1, APOA1, CXCL8, MMP1, MMP3, and THBS1) in tumor tissue were identified by the differential analysis of 10 hub genes." (PMID 35719376, 2022). "Specifically, serum APOA-1 levels were significantly correlated with differences in hs-CRP (p = 0.003), HBsAg (p < 0.001), tumor number (p < 0.001), Child-Pugh score (p = 0.027), and BCLC stage (p = 0.041)." (PMID 34790226, 2021). "However, ApoA1 mimetic peptides may exert anti-tumor effects via mechanisms distinct from ApoA1." (PMID 32411725, 2020). "Collectively, the reduction in ApoA1 transcription, intracellular and secreted ApoA-I, and circulating HDL levels in HCC hint to a putative tumor suppressor role of this pathway." (PMID 31374929, 2019). "Only 3 genes (APOA1, MAP3K4 and MMP14) were confirmed to be downregulated in radiosensitive tumours in the preoperative setting." (PMID 30285791, 2018). "This study demonstrates novel data on the relationships between tumor characteristics in CRC and serum APOA1 and APOB levels and APOB/APOA1 ratio." (PMID 28710487, 2017). "For example, we showed that the mRNA levels of transferrin (TF), Apolipoprotein A1 (APOA1) and hepatocyte nuclear factor 4-alpha (HNF4α) were significantly altered in AA liver (cirrhotic) and tumor samples compared to CA." (PMID 28938650, 2017). "In addition, ApoA-1 might impair extracellular matrix degradation properties of tumor cells." (PMID 27683106, 2016). "Only tumor circumferential extent (P = 0.014) and ApoA1 (P = 0.038) were independent predictors for TRG 0-1, while for good down-staging, only age (P = 0.02) and tumor circumferential extent (P = 0.004) were independent predictors." (PMID 26646794, 2016). "Apolipoprotein A1, the most important proteic component of HDL-c, in vitro has a direct suppressive effect on tumor cells, and in vivo prompts tumor-infiltrating macrophages towards tumor rejection." (PMID 27603338, 2016). "We found that the serum ApoA-1 level was significantly lower in HCC patients with tumor recurrence, and was an independent indicator of tumor-free survival and overall survival." (PMID 27683106, 2016). "The proteomic clusters included tumor upregulated (PRDX3, APOA1, CLIC1) and downregulated (NFM, NDUS1, MDHC, ALDOC, STMN1, PEBP1, DDAH1, CN37) proteins." (PMID 25050814, 2014). "S100A9, which we found up-regulated in pT1-HG biopsies, was identified as a protein associated with iNOS activity, and it is also involved in the regulation of signal transduction, such as SOD2, APOA1, HSP90, HSPA5, HINT1, MYDGF, and SerpinB3, and in immunomodulation in tumor microenvironments." (PMID 41441336, 2025). "Following intervention with the cholesterol inhibitor MβCD, the expression of cholesterol synthesis-related proteins (CD36, SREBP2 and HMGCR) decreased, while the expression of cholesterol efflux-related proteins (APOA1 and ABCG1) increased, leading to significant inhibition of tumor cell growth." (PMID 41041664, 2025).
tumor (continued). "Augmented APOA1 reflects its potential role in driving therapeutic resistance and disease progression by reprogramming the lipid metabolic network of tumor cells; APOB, APOC3, and APOH may function like APOA1." (PMID 39318189, 2024). "However, ApoA1 treatment significantly promoted CD8+ T-cell proliferation when cells with TAMs, CD8+ T cells, and tumor cells were in contact." (PMID 37474548, 2023). "APOA1 also regulates inflammation signals through the STAT3 signaling pathway and reduces matrix metalloproteinase-9 (MMP-9) levels, which is an important factor that promotes tumor proliferation and metastasis." (PMID 35421932, 2022). "Interestingly, APOA1, FASN, FABP4, and LPL were oppositely dysregulated in liver and lung metastasis compared to the primary CRC tumour, whereas AGPAT1 was found to be significantly upregulated in lung metastasis." (PMID 35957902, 2022). "After APOA1’s involvement in the human immune response was revealed via enrichment analysis, we searched the TIMER database to reveal any correlation between APOA1 expression and infiltrating immune cells and tumor purity." (PMID 35858961, 2022). "AAV-mediated overexpression of APOA1 and rHDL injections decreased PDAC tumor development in vivo." (PMID 35577388, 2022). "By using a model of inherited breast cancer, transgenic overexpression of human APOA1 did not result in inhibition of tumor growth." (PMID 35577388, 2022). "Subcutaneous injection of human ApoA1 to mice lacking ApoA1, prevented the formation and progression of tumours and reduced the size and growth of established tumours." (PMID 36050733, 2022). "FN1, APOA1, CXCL8, MMP1, MMP3, and THBS1 were significantly upregulated in the tumor samples." (PMID 35719376, 2022). "In addition to the robust induction of type I and type III interferons, expression of APOA1, APOL1, APOL3, and CH25H was increased from 10 to >50-fold, depending on the cell line (C1 or C2) from which the tumor originated." (PMID 34983824, 2022). "In this study, an Apolipoprotein A1 (ApoA1)-modified cationic liposome containing a synthetic cationic lipid and cholesterol was developed for the delivery of a small-molecule chemotherapeutic drug, doxorubicin (Dox) to treat MDR tumor." (PMID 33652957, 2021). "Unlike previous studies, our study revealed that APOA-1 DNA methylation levels in HCC tissues were lower than those in non-tumor tissues." (PMID 34790226, 2021). "On the other hand, neither transgenic overexpression of human ApoA1 nor ApoA1 knockout affected LPA levels in tumor-bearing mice." (PMID 32411725, 2020). "We demonstrated that low serum APOA1 levels associated with advanced T-class and TNM-stage but low serum APOB levels did not significantly correlate with tumor characteristics." (PMID 28710487, 2017). "In conclusion, low serum APOA1 levels are associated with advanced stage and systemic inflammation, while serum APOB does not significantly correlate with tumor stage." (PMID 28710487, 2017). "Specifically, we found negative correlations between serum APOA1 levels and tumor stage, especially T-class, and WHO grade." (PMID 28710487, 2017). "Using the optimal cutoff value (1.04 g/L), a higher positive rate of patients with a low ApoA-1 level was observed in patients with tumor recurrence compared with patients without recurrence (46.79% vs. 26.96%, p<0.05)." (PMID 27683106, 2016). "Furthermore, the correlation between the ApoA-1 level and the circulating tumor cell (CTC) level was explored, and the effect of ApoA-1 on HCC cell lines was investigated." (PMID 27683106, 2016). "APOA1 showed positive immunoreactivity but its expression did not correlate with Dukes’ staging (p = 0.314), tumour grading (p = 0.880) and lymph node involvement (p = 0.108)." (PMID 26463353, 2016). "The serum ApoA-1 level could therefore serve as a useful prognostic marker for HCC, potentially reflecting the survival of tumor cells during their hematogenous dissemination." (PMID 27683106, 2016).
tumor (continued). "Additionally, the statistically significant differences in APOA1 levels before and after treatment in patients achieving CR and PR confirmed that downregulation of APOA1 expression promotes DLBCL progression by reducing cholesterol efflux in tumor cells." (PMID 41041664, 2025). "Furthermore, the tumor-like behavior of PAS trophoblasts - exhibiting both hyperinvasive properties and malignant proliferation patterns - provides additional rationale for investigating APOA1’s role." (PMID 40778280, 2025). "In their study, samples from three groups (PA, residual PA, and CXPA) were analyzed to identify protein signatures and their results suggested that seven proteins (APOA1, AP1M1, SYCP1, DCD, HBB, HP, and SLC4A1) could be potential signatures for tumor progression or suppression." (PMID 39155517, 2025). "Indeed, treatment with ApoA1 alone did not increase tumor cell clearance in TAMs or T cells alone, but cocultivation of TAMs and T cells in the presence of ApoA1 significantly increased tumor kill." (PMID 37474548, 2023). "Moreover, ApoA1-lip/Dox had a longer half-life and enhanced tumor targeting, which enhanced the anti-tumor effect of Dox with no obvious toxicity in vivo." (PMID 33652957, 2021). "On the basis of our identification of an association between markers in the blood and the densities of immune cells in the tumor microenvironment, we proposed that the CEA level, number of monocytes, LMR, and ApoA1 may be used to ascertain the immunological status in the tumor microenvironment." (PMID 31300050, 2019). "In addition, the ApoA1 mimic peptides in bLP may provide an opportunity to simulate the nanostructure and biological properties of HDL to enhance the tumor targeting ability." (PMID 31346166, 2019). "EMT is considered as a major mechanism involved in the dissemination of tumor cells in HCC, However, our current data showed that ApoA-1 treatment might inhibit CTC formation via EMT-independent mechanism, in which the expressions of MMP2, MMP9, and VEGF were strongly down-regulated." (PMID 27683106, 2016). "However, matrix metalloproteinases (MMPs) including MMP-2 and MMP-9 showed significant decrease after ApoA-1 treatment in both two cell lines, which indicating ApoA-1 might inhibit CTC formation via impairing extracellular matrix degradation properties of tumor cells." (PMID 27683106, 2016). "Tumor CyTOF and histology showed T-cell and microglial enrichment in SB28 but not GL261 after Apoa1 or Il1b gene therapy treatments." (PMID 40161763, 2025). "Strong immunoreactivity of ESR1, APOA1, IGF1, and PON1 was observed in normal tissues, whereas weak or no staining was observed in tumor tissues." (PMID 40317014, 2025). "ApoA1 treatment did not enhance CD8+ T-cell proliferation without cell-to-cell contacts with TAMs and tumor cells, suggesting that cytokine networks were dispensable for the TAM-T-cell axis." (PMID 37474548, 2023). "PC patients presented a serum lipids difference from non-PC tumor patients in triglyceride (P=0.001), cholesterol (P=0.005), HDL (P<0.001), LDL (P=0.003), apolipoprotein A1 (P=0.001), apolipoprotein B (P=0.007), and apolipoprotein E (P<0.001)." (PMID 34335950, 2021). "The expressions of APOB, FGA, FGG, APOA1, and F2 were significantly down-regulated in the TCGA-LIHC cohort (P<0.05), but SERPINC1 levels were not significantly different between normal and tumor tissues (P>0.05)." (PMID 33834191, 2021). "Differential gene expression between responders (NR = 30) and non-responders (NNR = 12) was observed for APOA1, MAP3K4 and MMP14 genes with over 2-fold downregulation in pRT-responsive tumours." (PMID 30285791, 2018). "Although the exact molecular mechanism of apoA-I/HDL anti-tumor activity is not known, studies with the syngeneic B16F10L tumors comparing those from apoA1 transgenic vs. A-I KO mice revealed that the overall net impact of host apoA-I on the tumor microenvironment is profound and manifold." (PMID 26617517, 2015).
cancer (163 papers, 2008 to 2025). A tumor composed of atypical neoplastic, often pleomorphic cells that invade other tissues. "Some studies report that the ApoB/ApoA1 ratio is associated with the increase of overall cancer incidence in males." (PMID 39252808, 2024). "Many studies have indicated that some specific lipids, such as polyunsaturated fatty acids 3, 4, cholesterol 5-7, HDL cholesterol 8-10, LDL cholesterol 11, apolipoprotein A1 12, 13, are inversely associated with cancer risk." (PMID 38434974, 2024). "Low apolipoprotein A1 level is linked to a high cancer risk, systemic inflammatory response and poorer survival in some cancers, including oesophageal squamous cell carcinoma." (PMID 38263244, 2024). "Multivariable Cox proportional hazard regression analysis adjusted by cancer‐related prognostic factors, such as smoking status, identified the elevated ApoA1 as an independent predictor of decreased risk of total and gastrointestinal cancer mortalities." (PMID 35796324, 2022). "In the past years, a correlation between serum ApoA1 level and disease risk has been observed in many cancer types." (PMID 35100989, 2022). "It has been demonstrated that apolipoproteins A1(ApoA1) are associated with disease risk in many cancer types." (PMID 35100989, 2022). "Our study demonstrates the prognostic implication of preprocedural ApoA1 for predicting future risk of cancer mortality in patients undergoing PCI." (PMID 35796324, 2022). "Multivariate Cox proportional hazard analyses adjusted by traditional risk factors, as well as those previously indicated to associate with cancer incidence and mortality, showed lower ApoA1 increased the risk of total and GI cancer mortalities." (PMID 35796324, 2022). "Nevertheless, as the association between ApoA1 and cancer mortality in this population has been rarely addressed, our study aimed to evaluate prognostic impact of ApoA1 on multiple types of cancer mortality after PCI." (PMID 35796324, 2022). "Considering that oxidative stress and inflammation were strongly associated with cancer growth, the ApoA1 antioxidant and anti-inflammatory activities were of interest in the context of cancer progression." (PMID 34298850, 2021). "In two independent Danish cohorts totaling 116,728 individuals and up to 25 years of follow-up, we found that low levels of HDL cholesterol and apolipoprotein A1 were associated with increased risk of several cancers." (PMID 32998735, 2020). "Low levels of HDL cholesterol and apolipoprotein A1 were associated with increased risk of any cancer in the Copenhagen General Population Study." (PMID 32998735, 2020). "Kaplan-Meier curves visualized that high serum APOA1 levels significantly associated with better cancer-specific survival (CSS) (61.9% vs. 84.3%, P = < 0.001) and OS (45.2% vs. 79.4%, P = < 0.001)." (PMID 28710487, 2017). "Low levels of HDL cholesterol and/or apolipoprotein A1 were linked to a higher risk of breast cancer, lung cancer, nervous system cancer, non-Hodgkin lymphoma, and myeloproliferative neoplasm among twenty-seven different cancer types." (PMID 38540127, 2024). "Another DEG associated with cancer revealed in BPA-treated tissues is Apolipoprotein A1 (APOA1)." (PMID 38074096, 2023). "For example, in the case of Apolipoprotein A1 (ApoA1), some studies found that alteration in its levels was associated with cardiovascular outcomes and it has also been evaluated as a diagnostic and prognostic marker for some cancers." (PMID 37420190, 2023). "Moreover, as illustrated by the cubic spline curve of serum ApoA1 level, the risk for future cancer mortality following PCI appeared to be inversely associated and the relationship was linear." (PMID 35796324, 2022). "Moreover, cohort studies in particular have indicated that levels of HDL and ApoA1 were inversely associated with the incidence of cancer and cancer mortality in general populations." (PMID 35796324, 2022).